JADE3 (jade family PHD finger 3)
Description:
Scaffold subunit of some HBO1 complexes, which have a histone H4 acetyltransferase activity.
Synonyms: KIAA0215; PHF16; JADE-3
Tractability: PROTAC: ubiquitination databases record sites on it.
Gene: Protein-coding gene on chromosome X (46,912,276 to 47,061,242, forward strand). Ensembl gene ENSG00000102221.
Subcellular location (Human Protein Atlas): Nucleoli; Nucleoplasm
Pathways (Reactome):
Chromatin organization: HATs acetylate histones
Gene Ontology:
Molecular function: protein binding; histone reader activity
Biological process: regulation of cell cycle; regulation of DNA biosynthetic process; regulation of DNA replication; chromatin organization
Cellular component: histone acetyltransferase complex; nucleoplasm
Homologues: Orthologues: chimpanzee JADE3 (99% identical), macaque JADE3 (99% identical), pig JADE3 (91% identical), dog JADE3 (87% identical), guinea pig JADE3 (87% identical), rabbit JADE3 (86% identical), rat Jade3 (83% identical), mouse Jade3 (82% identical), tropical clawed frog jade3 (67% identical), zebrafish jade3 (60% identical), Drosophila melanogaster rno (42% identical), Caenorhabditis elegans phf-15 (19% identical). Paralogues in human: JADE1 (44% identical), JADE2 (39% identical), BRPF3 (26% identical), BRD1 (24% identical), BRPF1 (24% identical), PHF14 (17% identical), MLLT6 (15% identical), MLLT10 (15% identical).
Diseases named in the same sentence as JADE3 in open-access papers:
JADE3 is named in the same sentence as 8 diseases in open-access papers, as found by Europe PMC text mining. Sharing a sentence is not in itself a finding about the gene and the disease. The quoted sentences say what the papers report.
breast carcinoma (3 papers, 2022 to 2025). "Nevertheless, our findings suggested that circAAGAB inhibited breast cancer progression through the circAAGAB-miR-378 h-KIAA1522/NKX3-1/JADE3 axis and could serve as a novel biomarker or target for therapy." (PMID 36899354, 2023).
colon cancer (2 papers, 2019 to 2023). "The JADE3 (Jade family PHD finger 3) gene, which acetylates the histone during the transcription, was found upregulated in colon cancer cell line." (PMID 31244652, 2019).
cancer (6 papers, 2019 to 2025). A tumor composed of atypical neoplastic, often pleomorphic cells that invade other tissues. "JADE family members JADE2 and JADE3 are key members involved in chromatin remodeling and cell cycle regulation, surface as a hallmark of cancer progression." (PMID 38813086, 2024). "Jade family PHD finger 3 (JADE3) is related to cell proliferation and apoptosis and increases cancer stem cell-like properties along with SOX9." (PMID 41440381, 2025). "JADE3 contributes to chromatin remodeling through histone acetylation, promoting transcriptional activation of key cancer-related genes." (PMID 38813086, 2024). "By fostering cancer stem cell-like properties through interaction with critical gene promoters, such as LGR5, JADE3 directly influences tumor initiation and growth." (PMID 38813086, 2024).
JADE3 also shares sentences with these, for which no sentence is quoted: colorectal cancer (1 paper); hepatocellular carcinoma (1); lung carcinoma (1); prostate carcinoma (1); tumor (1).